ARHGAP32 (Rho GTPase activating protein 32)
Description:
GTPase-activating protein (GAP) promoting GTP hydrolysis on RHOA, CDC42 and RAC1 small GTPases. May be involved in the differentiation of neuronal cells during the formation of neurite extensions. Involved in NMDA receptor activity-dependent actin reorganization in dendritic spines. May mediate cross-talks between Ras- and Rho-regulated signaling pathways in cell growth regulation. Isoform 2 has higher GAP activity (By similarity).
Synonyms: GRIT; KIAA0712; RICS; MGC1892; GC-GAP; PX-RICS; p200RhoGAP; p250GAP
Tractability: Antibody: UniProt places it where antibodies can reach, with high confidence. PROTAC: ubiquitination databases record sites on it; its protein half-life has been measured.
Gene: Protein-coding gene on chromosome 11 (128,965,060 to 129,279,324, reverse strand). Ensembl gene ENSG00000134909.
Subcellular location: Postsynaptic density; Cell projection, dendritic spine; Cytoplasm, cell cortex; Endosome membrane; Golgi apparatus membrane; Endoplasmic reticulum membrane; Membrane
Subcellular location (Human Protein Atlas): Golgi apparatus; Cytosol; Nucleoli fibrillar center; Nucleoplasm
Pathways (Reactome):
Signal Transduction: CDC42 GTPase cycle; RAC1 GTPase cycle; RAC2 GTPase cycle; RAC3 GTPase cycle; RHOA GTPase cycle; RHOB GTPase cycle; RHOC GTPase cycle; RHOD GTPase cycle; RHOF GTPase cycle; RHOG GTPase cycle; RHOJ GTPase cycle; RHOQ GTPase cycle
Cell-Cell communication: Regulation of CDH1 posttranslational processing and trafficking to plasma membrane
Gene Ontology:
Molecular function: protein binding; GTPase activator activity; phosphatidylinositol binding; phosphatidylinositol phosphate binding
Biological process: regulation of dendritic spine morphogenesis; regulation of postsynapse assembly; regulation of small GTPase mediated signal transduction; small GTPase-mediated signal transduction; signal transduction
Cellular component: cytosol; endosome membrane; Golgi apparatus; Golgi membrane; membrane; endoplasmic reticulum membrane; glutamatergic synapse; postsynaptic density; cell cortex; cytoplasm; dendritic spine
Genetic constraint (gnomAD): Loss-of-function variants: 41 observed, 152.37 expected, observed/expected ratio (o/e) 0.27, 90% interval 0.21 to 0.35. The upper end of that interval is the gene's LOEUF score, 0.35, which puts it in group 1 of 6, group 1 being the genes least tolerant of losing a copy. Missense variants: 2,080 observed, 2,542.7 expected, observed/expected ratio (o/e) 0.82, 90% interval 0.79 to 0.85. Synonymous variants: 902 observed, 949 expected, observed/expected ratio (o/e) 0.95, 90% interval 0.9 to 1.
Homologues: Orthologues: chimpanzee ARHGAP32 (99% identical), macaque ARHGAP32 (98% identical), dog ARHGAP32 (89% identical), mouse Arhgap32 (87% identical), rat Arhgap32 (87% identical), guinea pig ARHGAP32 (86% identical), pig ARHGAP32 (86% identical), rabbit ARHGAP32 (85% identical), tropical clawed frog arhgap32 (52% identical), zebrafish arhgap32b (48% identical), zebrafish arhgap32a (36% identical), Drosophila melanogaster CdGAPr (21% identical), and 1 more. Paralogues in human: ARHGAP33 (25% identical), ARHGAP31 (16% identical), ARHGAP30 (16% identical).
Diseases named in the same sentence as ARHGAP32 in open-access papers:
ARHGAP32 is named in the same sentence as 24 diseases in open-access papers, as found by Europe PMC text mining. Sharing a sentence is not in itself a finding about the gene and the disease. The quoted sentences say what the papers report.
schizophrenia (4 papers, 2012 to 2023). A major psychotic disorder characterized by abnormalities in the perception or expression of reality. "Taken together, our present results suggest that both ARHGAP32 and ARHGAP33 may be involved in the pathophysiology of schizophrenia." (PMID 26839058, 2016). "In this respect, ARHGAP33 and ARHGAP32 as well as SORT1 are unique in that they are regulators of intracellular protein trafficking, highlighting a novel role of the SNX-related proteins in the pathophysiology of schizophrenia." (PMID 26839058, 2016).
Jacobsen syndrome (3 papers, 2016 to 2026). A multiple congenital anomaly/intellectual disability contiguous gene syndrome caused by partial deletion of the long arm of chromosome 11. "ARHGAP32 (11q24.3) has been implicated as a candidate gene for Autism Spectrum Disorder (ASD) in Jacobsen syndrome, where a 243-kb terminal deletion encompasses its locus." (PMID 41726838, 2026).
autism (2 papers, 2016 to 2018). Persistent deficits in social interaction and communication and interaction as well as a markedly restricted repertoire of activity and interest as well as repetitive patterns of behavior.
breast carcinoma (2 papers, 2015 to 2020). "The most interesting alteration was an 11q24.3 loss harboring ARHGAP32, a gene earlier reported to be involved in fusion events in breast cancer cell lines and to participate in autophagy processes." (PMID 25391423, 2015).
alexithymia (1 paper, 2024). An agnosia that is a deficiency in understanding, processing, or describing emotions. "The exome association analysis detected four significant variants (ABCB4 gene: rs45575636, TP53AIP1 gene: rs35942033, ARHGAP32 gene: rs35287114, and TMEM88B gene: rs144957058) associated with alexithymia." (PMID 39202385, 2024). "Furthermore, there are other genes related to alexithymia risk, such as VDBP, TP53AIP1, ARHGAP32, and TMEM88B." (PMID 39202385, 2024).
proteinopathies (1 paper, 2025). "STMN2 encodes an axonal protein that has been extensively studied in the field of TDP-43 proteinopathies, while ARHGAP32, despite being identified in several studies, had not been highlighted for its relevance to the cryptic exon in this gene." (PMID 40478310, 2025).
cancer (4 papers, 2019 to 2024). A tumor composed of atypical neoplastic, often pleomorphic cells that invade other tissues. "ARHGAP32 is known to influence cell proliferation and differentiation, and it is also identified as a risk gene for neurodevelopmental disorders and a potential therapeutic target for cancer treatment." (PMID 39061594, 2024).
tumor (2 papers, 2017 to 2018).
neurodegenerative disease (1 paper, 2025). A disorder of the central nervous system characterized by gradual and progressive loss of neural tissue and neurologic function. "Together these analyses suggest that splicing alterations observed in STMN2 and ARHGAP32 likely resulted from TDP-43 dysfunction, whereas most of the other observed splicing alterations resulted from general neurodegenerative disease processes." (PMID 40478310, 2025).
ARHGAP32 also shares sentences with these, for which no sentence is quoted: autism spectrum disorder (2 papers); congenital heart defects (2); depression (2); epilepsy (2); neurodevelopmental disorder (2); amyotrophic lateral sclerosis (1); Anxiety (1); attention deficit-hyperactivity disorder (1); Cognitive impairment (1); gastric cancer (1); injury (1); neuroblastoma (1); Parkinson disease (1); psychological distress (1); sleep disorder (1).